CENPL (centromere protein L)
Diseases named in the same sentence as CENPL in open-access papers:
CENPL is named in the same sentence as 42 diseases in open-access papers, as found by Europe PMC text mining. Sharing a sentence is not in itself a finding about the gene and the disease. The quoted sentences say what the papers report.
breast carcinoma (7 papers, 2021 to 2024). "In conclusion, CENPL may act on immune cells that have invaded the tumor as well as tumor cells to cause a harmful role in the development of breast cancer." (PMID 36816951, 2023). "We also examined the link between CENPL expression and immune cell infiltration because it is essential for patients with breast cancer to have immune cell infiltration." (PMID 36816951, 2023). "Next, we evaluated CENPL expression in multiple breast cancer cell lines and found relatively higher expression of CENPL in MCF-7, MDA-MB-231, MDA-MB-468, and SKBR3 cells compared with that in MCF-10 cells." (PMID 36816951, 2023). "Cellular research verified that CENPL knockdown dramatically reduced the proliferation and migration of breast cancer cells." (PMID 36816951, 2023). "In light of these findings, breast cancers with high CENPL expression have multiple oncogenic pathways hyperactivated, including those that regulate cell proliferation." (PMID 36816951, 2023). "We used TCGA data to conduct correlation analysis between CENPL and all other mRNAs in breast cancer in order to more effectively investigate the roles and pathways involved by CENPL." (PMID 36816951, 2023). "Scratch testing and the transwell assay were used to evaluate the effects of CENPL on breast cancer cell migration." (PMID 36816951, 2023). "The results obtained show that CENPL was upregulated in breast cancer, lung cancer, colorectal cancer, gastric cancer, liver cancer, cervical cancer, and ovarian cancer." (PMID 35844598, 2022). "Our findings suggest that CENPL may be an oncogene in breast cancer and a predictor of efficacy of immunotherapy for breast cancer." (PMID 36816951, 2023). "Taken together, CENPL facilitates the proliferation and migration of breast cancer cells." (PMID 36816951, 2023). "Besides, CENPL silencing also significantly impaired the migratory ability of breast cancer cells as evidenced by the Transwell assay and scratch test." (PMID 36816951, 2023). "We also investigated at just how CENPL expression correlates to breast cancer’s molecular pathways." (PMID 36816951, 2023). "Our findings imply that CENPL might be a driver gene in breast cancer; however, as its mode of action is yet unknown, more research is required." (PMID 36816951, 2023). "Breast cancer was one of numerous tumor forms with high CENPL expression." (PMID 36816951, 2023). "Breast cancer cells’ ability to proliferate and migrate was decreased by CENPL knockdown." (PMID 36816951, 2023). "Finally, we assessed at how CENPL knockdown affected breast cancer cells’ ability to proliferate and migrate." (PMID 36816951, 2023). "Moreover, CENPL was detected as one of the novel hub genes and served as a prognostic marker candidate in breast cancer, and high expression of CCNB2 in breast carcinoma showed an association with disadvantageous clinical outcomes." (PMID 36077657, 2022). "Considering the five hub genes, which were identified based on PPI networks and WGCNA, share the same signaling pathways during breast cancer progression, we conducted correlation analysis between the four novel hub genes (CENPL, ISG20L2, LSM4 and MRPL3) and EZH2." (PMID 34341433, 2021). "However, the relationship of CENPL with breast cancer remains unknown." (PMID 36816951, 2023). "DiseaseMeth version 2.0 analysis displayed that the mean methylation levels of CENPL, MRPL3 and LSM4 were all significantly reduced in breast cancer compared to normal breast tissues (P < 0.05)." (PMID 34341433, 2021). "The expression levels of each hub gene (CENPL, ISG20L2, MRPL3, and LSM4) was correlated with EZH2 in three different breast cancer cell lines (p < 0.01)." (PMID 34341433, 2021). "Based on the TCGA_BRCA and match TCGA normal and GTEx data of GEPIA database, the mRNA expression levels of these genes (CENPL, ISG20L2, MRPL3 and LSM4) were also significantly higher in breast cancer tissues than normal tissues." (PMID 34341433, 2021).
breast carcinoma (continued). "To further elucidate the lurking biological functions of CENPL, ISG20L2, MRPL3 and LSM4 in breast cancer occurrence and development, we conducted GSEA and GSVA using METABRIC dataset." (PMID 34341433, 2021). "Both CENPL and CCNB1 have been found to be upregulated in breast cancer tissues." (PMID 36982402, 2023). "The negative effect of CENPL on breast cancer cell proliferation was further confirmed by colony-formation assay." (PMID 36816951, 2023). "To explore the biological effects of CENPL on breast cancer cell proliferation, we knocked down CENPL expression in MDA-MB-231 and MCF-7 cells via two CENPL siRNA, and validated the successful silence of CENPL expression in these two cell lines." (PMID 36816951, 2023). "We looked into the connection between CENPL expression and distant metastasis-free survival (DMFS) and relapse-free survival (RFS) in the TCGA cohort to analyze the efficacy of CENPL expression in predicting the prognosis of breast cancer patients." (PMID 36816951, 2023). "As an oncogene, growing evidence has identified EZH2 was closely related to breast cancer development and progression through multiple molecular mechanisms, but no studies are related to the roles of CENPL, ISG20L2, MRPL3 and LSM4 in breast cancer." (PMID 34341433, 2021). "In DiseaseMeth 2.0 database, the correlation analysis of DNA methylation patterns of hub genes with mRNA expression revealed that CENPL, MRPL3 and LSM4 were hypomethylated in breast cancer samples compared with adjacent normal ones, while ISG20L2 was hypermethylated in breast cancer sample." (PMID 34341433, 2021). "Generally speaking, the DNA methylation patterns negatively correlates with mRNA expression, which is consistent with the observed up-regulation of CENPL, MRPL3 and LSM4 in breast cancer, while the latest research suggested DNA hypermethylation can lead to mRNA upregulation." (PMID 34341433, 2021). "Additionally, genetic alterations of CENPL, ISG20L2, MRPL3, and LSM4 were further examined in cBioPortal database, showing these four hub genes were altered in 570 (26%) of 2173 breast cancer patients." (PMID 34341433, 2021). "With regard to BRCA breast cancer in the TCGA cohort, elevated CENPL expression was seen in both the unpaired samples and the paired samples, and images of protein expression of CENPL were obtained from the HPA, suggesting that CENPL may play a role in the pathogenesis of breast cancer." (PMID 36816951, 2023). "Among these, many studies on EZH2 in breast cancer have been reported, but no studies are related to the roles of CENPL, ISG20L2, MRPL3 and LSM4 in breast cancer." (PMID 34341433, 2021).
esophageal cancer (3 papers, 2021 to 2022). A primary or metastatic malignant neoplasm involving the esophagus. "Therefore, we investigated the expression and prognostic value of CENPL in esophageal carcinoma (ESCA), stomach adenocarcinoma (STAD), pancreatic adenocarcinoma (PAAD), colon adenocarcinoma (COAD) and rectum adenocarcinoma (READ)." (PMID 36572856, 2022).
gastric cancer (3 papers, 2022). A primary or metastatic malignant neoplasm involving the stomach. "Levels of CENPL mRNA in colorectal and gastric cancers and PAAD were higher than those in para-tumor tissues (p < 0.01 for all)." (PMID 36572856, 2022).
hepatocellular carcinoma (3 papers, 2021 to 2022). A malignant tumor that arises from hepatocytes. "In our previous study it was found that CENPL was overexpressed in hepatocellular carcinoma and significantly predicted patient's prognosis." (PMID 36572856, 2022). "In our previous study it was found that CENPL was overexpressed in hepatocellular carcinoma and predicted the prognosis of patients, and the overexpression of CENPL was positively correlated with the abundance of various tumor infiltrating lymphocytes." (PMID 36572856, 2022).
lung adenocarcinoma (3 papers, 2022 to 2023). A carcinoma that arises from the lung and is characterized by the presence of malignant glandular epithelial cells. "Here, we studied the role of CENPL in pan-cancer and further verified the results in lung adenocarcinoma (LUAD) through in vitro experiments." (PMID 35844598, 2022). "NDC80, CENPL, ORC1, CENPN, CCNE1, and CCNB2 were significantly upregulated in the TCGA cohort as well as in the 18 pairs of lung adenocarcinoma patient samples, and high expression was significantly associated with poor prognosis in lung adenocarcinoma." (PMID 37123398, 2023).
pancreatic cancer (3 papers, 2021 to 2024). "Previous studies have demonstrated significantly elevated expression of CENPL in liver, breast, and pancreatic cancer samples compared to normal samples, suggesting that high expression of CENPL may serve as a potential prognostic indicator for patients with liver, breast, and pancreatic cancers." (PMID 38382106, 2024).
CNS cancer (2 papers, 2021 to 2022). "By contrast, CENPL was downregulated in the brain and CNS cancer and leukemia." (PMID 35844598, 2022).
lung carcinoma (2 papers, 2021 to 2022). "Furthermore, CENPL was significantly upregulated in lung cancer cell lines as well." (PMID 35844598, 2022).
testicular germ cell tumor (2 papers, 2021 to 2022). A germ cell tumor arising from the testis. "CENPL was associated with the stage of kidney renal papillary cell carcinoma (KIRP), adrenocortical carcinoma (ACC), LIHC, kidney chromophobe (KICH), LUAD, and testicular germ cell tumors (TGCT)." (PMID 35844598, 2022). "However, CENPL was decreased in Acute Myeloid Leukemia (LAML) and testicular germ cell tumor (TGCT) in GEPIA, which indicated that the transcription level of CENPL was still specific in different tumors." (PMID 34607313, 2021).
breast invasive cancer (1 paper, 2022). "The mutation analysis showed that CENPL mutation was associated with worse OS, DFS, DSS, and PFS in breast invasive carcinoma." (PMID 35844598, 2022).
endometrial carcinoma (1 paper, 2022). A malignant tumor arising from the epithelium that lines the cavity of the uterine body. "There were 42 kinds of cancers with CENPL alteration and uterine mixed endometrial carcinoma had the highest frequency of 14.29%." (PMID 35844598, 2022).
growth deficiency (1 paper, 2019). "Moreover, they proposed that deletions of two of the genes within the SRO, namely, the dynamin 3 gene (DNM3) and the centromere protein L gene (CENPL), were potential causes of intellectual disability and growth deficiency, respectively." (PMID 31645985, 2019).
Infertility (1 paper, 2022). "This search revealed that in the case of NANOS1 overexpression, three infertility related genes (CREBBP, CCNB1, and NPAS2) and five cancer-germ cell genes (CENPL, ERCC6L, KIF18A, SIAH1, and TRIM71) were present in three clusters." (PMID 35743036, 2022).
lymph node metastasis (1 paper, 2021). "In this study, our data not only showed the expression level of CENPL, ISG20L2, LSM4 and MRPL3 were strongly associated with age, lymph node metastasis and higher SBR grade, but also significantly upregulated in triple negative breast cancer patients compared to non-triple negative breast cancer." (PMID 34341433, 2021).
thyroid carcinoma (1 paper, 2022). "However, CENPL was downregulated in thyroid carcinoma (THCA)." (PMID 35844598, 2022).
tumor (9 papers, 2021 to 2024). "Moreover, CENPL was associated with immune cell infiltration in pan-cancer, providing a potential immune therapy target for tumor treatment." (PMID 35844598, 2022). "Furthermore, CENPL was associated with immune cell infiltration in pan-cancer, providing a potential immune therapy target for tumor treatment." (PMID 35844598, 2022). "Similarly, the expression of the CENPL gene was positively associated with the tumor purity (p < 0.05)." (PMID 34457090, 2021). "In 275 cases of COAD and 349 cases of normal tissues, CENPL mRNA was significantly higher in tumor (p < 0.01)." (PMID 36572856, 2022). "We found that the mRNA levels of 4 out of 15 centromere proteins (CENPL, CENPQ, CENPR, and CENPU) were significantly higher in HCC than in normal tissues, and their mRNA levels were associated with the tumor stages (p values < 0.01)." (PMID 34457090, 2021). "This suggests that CENPL plays a critical role in regulating tumor immunology." (PMID 36816951, 2023). "Multivariate Cox regression analysis included CENPL mRNA, age, sex and tumor size (dichotomized with a cut-off value of 3.5 cm) and CENPL mRNA (HR = 1.74, CI = 1.05–2.9, p < 0.05) and age (HR = 1.03, CI = 1.01–1.1, p < 0.05) were independent risk factors for the prognosis of PAAD patients." (PMID 36572856, 2022). "We speculated that the occurrence and progression of HCC promoted by enhanced CENPL may be partly attributed to augmenting tumorigenic effect of macrophages and attenuating the anti-tumor effect of killer cells such as B cells, CD8+ T cells and CD4+ T cells." (PMID 34607313, 2021). "In addition, the expression of CENPL was positively correlated with the levels of the tumor-infiltrating lymphocytes." (PMID 34457090, 2021). "We have not yet verified the association between CENPL and tumor-infiltrating lymphocytes in human or mouse specimens." (PMID 34457090, 2021). "The analysis showed that high mRNA levels of CENPL, CENPQ, CENPR, and CENPU were significantly correlated with tumor stages (p < 0.01)." (PMID 34457090, 2021). "Then, we selected 4 CENPs (CENPL, CENPQ, CENPR, and CENPU) with high expression in HCC as shown in both the Oncomine and GEPIA databases to further analyze the relationship between mRNA levels and tumor stages." (PMID 34457090, 2021). "The expression of CENPL in tumor tissues (42%, 11/26) was higher than that in non-cancer tissues." (PMID 36572856, 2022). "In addition, CENPL, ESCO2, and CLSPN also serve important roles in tumor progression." (PMID 34556022, 2021).
cancer (6 papers, 2021 to 2025). A tumor composed of atypical neoplastic, often pleomorphic cells that invade other tissues. "The potential value of CENPL as a diagnostic and prognostic biomarker in pan-cancer was evaluated with the TCGA database and GEPIA." (PMID 35844598, 2022). "Next, we analyzed the association between CENPL and the stages of pan-cancers in the GEPIA2 website." (PMID 35844598, 2022). "Then we analyzed the diagnostic value of CENPL in various cancers using the ROC curve." (PMID 35844598, 2022). "We found that CENPL was significantly upregulated and was correlated with the clinical stage in several cancers, and the ROC curve analysis showed that CENPL may function as a diagnostic biomarker." (PMID 35844598, 2022). "The upregulation and mutation of CENPL were associated with a poorer prognosis in many cancers." (PMID 35844598, 2022). "The Cancer Genome Atlas (TCGA) and genotype-tissue expression across cancer data were used to investigate CENPL expression." (PMID 36816951, 2023). "In this study, we examined the relationship between CENPL expression and clinicopathological characteristics and prognosis in diverse cancers from The Cancer Genome Atlas (TCGA)." (PMID 36816951, 2023). "We examined the expression level of CENPL using pan-cancer TCGA and GTEx data obtained from the UCSC Xena database." (PMID 36816951, 2023). "Next, we further analyzed the correlation between CENPL and 14 cancer functional states using single-cell sequence data of CancerSEA." (PMID 35844598, 2022). "All in all, our results show that CENPL can function as an oncogene and immune infiltration-related biomarker in pan-cancer, especially LUAD." (PMID 35844598, 2022). "Through integrating multiple databases, we found that CNEPL was enhanced in most cancer types, which indicated that CENPL had a wide range of applicability and functional conservation." (PMID 34607313, 2021). "However, the correlation between CENPL expression and cancer development and immune infiltration has rarely been studied." (PMID 35844598, 2022). "Thus, we conducted a comprehensive analysis and assessed the potential value of CENPL in cancer diagnosis and prognosis." (PMID 35844598, 2022). "However, the understanding of CENPL in cancer is still limited." (PMID 36572856, 2022). "CENPL may function as a potential biomarker and oncogene in pan-cancer, especially LUAD." (PMID 35844598, 2022). "The results showed a significant positive correlation between CENPL and myeloid-derived suppressor cell (MDSC) infiltration and a negative correlation between CENPL and T-cell NK infiltration in most of the cancers." (PMID 35844598, 2022). "Among these genes, Nuf2 had the strongest positive correlation with CENPL in HCC and many other common cancers." (PMID 34607313, 2021). "Our results suggested a positive correlation between CENPL expression and MDSC infiltration and a negative correlation between CENPL and T-cell NK infiltration in most of the cancers." (PMID 35844598, 2022). "Previous researches have reported the role of CENPA, CENPE, CENPF in HCC, however, there is no research on the role of CENPL in HCC and other cancers." (PMID 34607313, 2021).
gastrointestinal tumors (1 paper, 2022). "In this study, we investigated the expression and prognostic value of CENPL in GI tumors, including ESCA, STAD, PAAD, COAD and READ, by using bioinformatic methods and immunohistochemical staining." (PMID 36572856, 2022). "In this study, the expression of CENPL mRNA in gastrointestinal tumors was analyzed using multiple public databases." (PMID 36572856, 2022). "Whether CENPL plays a role in the development and progression of other GI tumors remains unknown, and more studies are needed." (PMID 36572856, 2022). "Then, the prognostic value of CENPL in patients with gastrointestinal tumors was assessed." (PMID 36572856, 2022). "However, the expression and prognostic value of CENPL in other gastrointestinal tumors remain unknown." (PMID 36572856, 2022).
CENPL also shares sentences with these, for which no sentence is quoted: bladder urothelial carcinoma (2 papers); cervical cancer (2); colon adenocarcinoma (2); glioma (2); lung squamous cell carcinoma (2); ovarian carcinoma (2); stomach adenocarcinoma (2); acute myeloid leukemia (1); cholangiocarcinoma (1); colorectal cancer (1); gallbladder cancer (1); glioblastoma (1); head and neck squamous cell carcinoma (1); infection (1); Intellectual disability (1); kidney chromophobe (1); leukemia (1); liver cancer (1); Pan (1); pancreatic adenocarcinoma (1); rectum adenocarcinoma (1); skin cutaneous melanoma (1); triple-negative breast carcinoma (1); uterine corpus endometrial carcinoma (1).